USP14 (ubiquitin specific peptidase 14)
Diseases named in the same sentence as USP14 in open-access papers (continued):
Sharing a sentence is not in itself a finding about the gene and the disease.
tumor (continued). "This suggests that USP14 may affect the tumor activity of HCC by activating the Wnt/Notch1 signaling pathway." (PMID 40607251, 2025). "We hypothesize that USP14 regulates tumor growth and response to chemotherapy through interactions with BAG4 and PRKN, thereby influencing mitophagy and apoptosis pathways." (PMID 40316942, 2025). "USP14 plays a broad role in tumor malignancy and fat metabolism regulation." (PMID 39944823, 2025). "Given that USP14 has been linked to cisplatin resistance in HNSCC we hypothesized that USP14 may promote tumor progression by reducing ferroptosis through ROS clearance." (PMID 39928282, 2025). "Notably, we observed a strong correlation between USP14 mRNA levels and tumor grade; low USP14 expression prevalent in grade 1/2 tumors, while high USP14 expression was characteristic of grade 3/4 tumors." (PMID 39928282, 2025). "This study thoroughly demonstrates the theoretical correlation between ferroptosis and the degree of tumor immune response, further revealing that targeting USP14 to enhance ferroptosis plays a positive role in the remodeling of the tumor immune microenvironment post-RT." (PMID 40595451, 2025). "Additionally, USP14 was preferentially expressed in cells positive for ALDH1A3 in GBM tumor samples." (PMID 39990235, 2025). "Furthermore, the tumor inhibition rate, indicated by tumor weight, was markedly higher in the USP14-KO group (94.9%) compared to the USP14-WT group (72.5%)." (PMID 40595451, 2025). "The differential expression patterns observed in normal versus tumour tissues further support the role of USP14 in modulating S100A11 protein stability, which may impact cellular processes such as proliferation and metastasis." (PMID 40374593, 2025). "Additionally, researchers have reported that IU1, an inhibitor of USP14, can suppress cell growth and mitigate the tumor-promoting effects induced by YTHDF1 in GC cells." (PMID 41312360, 2025). "In conclusion, these results indicate that the strategy of targeting USP14 significantly amplifies the RT-induced enhancement of innate immune activation within tumors, derived from the augmented ferroptosis effect post-RT, rendering tumor cells immunogenic." (PMID 40595451, 2025). "Moreover, USP14 is involved in regulating ferroptosis, autophagy, amino acid metabolism, and immune suppression to mediate tumour progression and treatment response." (PMID 38228715, 2024). "Ubiquitin-specific peptidase 14 (USP14), a ubiquitin-specific protease associated with the proteasome, exerts essential functions in inflammation, cellular functions, neurodegenerative diseases, and tumor development." (PMID 38282961, 2024). "Given that USP14 promotes the proliferation, migration, and glycolytic metabolism in OSCC cells, we next assessed whether enhanced glycolysis mediated by USP14 upregulation in HN4 cells is necessary for its tumor-promoting effects." (PMID 38388430, 2024). "It is crucial to understand phospho-dependent USP14 activation because abnormal USP14 activity by AKT phosphorylation may promote tumor cell survival and proliferation by deregulating the global protein turnover rate." (PMID 38891087, 2024). "We therefore hypothesized that USP14 might act as a tumor-promoting factor during the progression of OSCC." (PMID 38388430, 2024). "Notably, our functional rescue experiments suggested that PFKL is a key factor that contributes to USP14’s tumor-promoting roles in OSCC." (PMID 38388430, 2024). "Moreover, microRNA-124a is identified as a tumor suppressor that targets USP14, reducing stemness and increasing the sensitivity of NSCLC cells to gefitinib." (PMID 38702734, 2024). "Similarly, 6-Gingerol has been found to inhibit USP14 ubiquitination, enhancing ferritin autophagy and ferroptosis to suppress tumor growth." (PMID 38519984, 2024). "This was then used to study the tumor-promoting effect of USP14 in vivo." (PMID 38388430, 2024).
tumor (continued). "Furthermore, in the subcutaneous tumour xenograft model, the expression of USP14 and FASN were increased, while the protein levels of GPX4 were decreased in the group with GSTM3 overexpression." (PMID 38228715, 2024). "Small-molecule inhibitors of USP14 may provide benefits in targeting tumor cells, but possible off-target effects are of major concerns with regard to treatments." (PMID 37711852, 2023). "In summary, these data indicated that the expression of HSF1 was significantly elevated in HNSCC tumor tissues compared to adjacent paired tissues, and its expression was correlated with lymph nodal metastasis, tumor grade, and USP14 expression in HNSCC patients." (PMID 37686660, 2023). "The xenograft tumor experiment checked the effect of USP14 overexpression on tumor cell growth." (PMID 37917013, 2023). "Interestingly, the inhibition of USP14 was showed to upregulate TNF-α expression in tumor cells and sensitize them to TNF-α and radiation-induced cytotoxicity." (PMID 37658402, 2023). "Additionally, relative to the sh-NC group, USP14 and XPO1 expressions in the tumor tissues were declined in the sh-USP14 group." (PMID 37082728, 2023). "In tumor tissues, USP14 upregulation dampened I-κB and strengthened NF-κB phosphorylation." (PMID 37917013, 2023). "Several miRNAs have been identified to target and regulate USP14, thus affecting tumor cells." (PMID 37917013, 2023). "However, Up284 did not broadly inhibit cellular DUBs or label proteins of molecular weight consistent with UCH37 or USP14 in tumor cell lysates." (PMID 37315065, 2023). "Further studies need to be performed to evaluate whether this treatment strategy works against tumor development and progression through specific inhibitors selectively targeting USP14." (PMID 36693850, 2023). "This notion is confirmed using the MC38 syngeneic mouse model, which shows that both USP14 knockdown and an inhibitor restrain tumor growth, increase the infiltration of cytotoxic T cells, decrease the infiltration of Tregs, and finally promote the response to anti-PD-1 therapy." (PMID 36163134, 2022). "Furthermore, the authors showed that miR-320a acts as a tumor suppressor by reducing vimentin expression and preventing USP14 from stabilizing this protein." (PMID 36497313, 2022). "For instance, increased expression of USP14 was observed in ESCC samples compared to that in their paired non-tumor tissues, and USP14 could be used for the prediction of unfavorable prognosis in ESCC." (PMID 35593463, 2022). "Furthermore, the number of cleaved caspase-3-positive tumor cells increased significantly in the combination treatment group, indicating that inhibition of USP14 together with anti-PD-1 was a highly effective therapeutic strategy for CRC." (PMID 36163134, 2022). "USP14 has been recognized as a key regulator of proliferation, apoptosis in tumor." (PMID 34420039, 2021). "Importantly, a synergic effect of oral administration of IU1 in combination with lentivirus-mediated USP14 knockdown on tumor growth inhibition was observed upon co-treatment of the two different ways to inhibit USP14 for 14 days." (PMID 34420039, 2021). "We herein found that IU1 as an inhibitor of USP14 could repress cell growth and restore the tumor-promoting effects induced by YTHDF1 in GC cells." (PMID 33791305, 2021). "Moreover, we provided the evidence to show that knockdown of USP14 or USP14 inhibitor (IU1) treatment inhibited tumor growth in tumor-bearing nude mice." (PMID 34420039, 2021). "Moreover, we provided the evidence to demonstrate that knockdown of USP14 or IU1 treatment inhibited tumor growth in mice." (PMID 34420039, 2021). "USP14 promotes tumor progress in HCC even under hypoxia conditions." (PMID 34420039, 2021). "We hypothesized that 6-Gingerol promotes rust disease and leads to tumor death by modulating USP14 expression and inducing Beclin 1-dependent autophagy." (PMID 33281606, 2020).
tumor (continued). "However, TRIM11-dependent tumor cell growth can be suppressed by USP14 overexpression in the HCT116 cell-derived xenograft model, which suggests possible opposing roles of USP14 in tumorigenesis." (PMID 32726943, 2020). "AKT-induced phosphorylation of USP14 may also promote tumor cell proliferation by regulating global proteomic turnover." (PMID 32726943, 2020). "We investigated whether USP14 inhibition suppresses tumor cell proliferation using the USP14 inhibitor IU1-47." (PMID 31653087, 2019). "Surprisingly, bioinformatics showed that miR-320a could target vimentin as well as directly bind USP14, which might contribute to the tumor suppressor role of miR-320a in GC." (PMID 27448976, 2017). "Another small molecule b-AP15 is first reported as a new tumor cell inhibitor to 19S regulatory-particle-associated deubiquitinases USP14 and UCHL5 activity without affecting 20S core-particle-associated proteolytic activity." (PMID 26097878, 2015). "Since we had seen that USP14 could promote glucose metabolism in OSCC cells and stabilize PFKL via deubiquitination, we reasoned that USP14 might exert tumor-promoting effects by upregulating the expression of PFKL and enhancing PFKL-mediated glycolysis in OSCC." (PMID 38388430, 2024). "Notably, the overexpression of PFKL in USP14-knockdown HN6 cells could significantly weaken the tumor-suppressing effects induced by depletion of USP14." (PMID 38388430, 2024). "Therefore, USP14 acts as a tumour promoter and may serve as a promising therapeutic target for NSCLC." (PMID 36969062, 2023). "Therefore, the regulatory function of USP14 on HIF1-α action revealed under hypoxia conditions in this work may also be applicable for the normoxic state in tumor cells." (PMID 34420039, 2021). "This process highlights a key mechanism through which USP14 controls BAG4 protein stability in CRC (MSI-H), offering insights into the USP14-BAG4 axis’s role in tumor biology and suggesting a potential therapeutic target for disrupting BAG4." (PMID 40316942, 2025). "The study found that USP14 and BAG4 were significantly overexpressed in tumor tissues compared to normal tissues, whereas PRKN expression was markedly reduced." (PMID 40316942, 2025). "USP14 stabilizes BAG4 via K48-deubiquitination, hindering Parkin-mediated mitophagy, which results in the accumulation of damaged mitochondria and fosters tumor progression." (PMID 40316942, 2025). "The knockdown of USP14 and UCHL5, or treatment with the inhibitor b-AP15, significantly impeded ATC cell proliferation, reduced metastasis capabilities, and suppressed tumor formation in nude mice models." (PMID 40804247, 2025). "Blocking USP14- SIRT1 axis by IU1, the USP14 inhibitor, significantly impeded macrophage polarization towards M2 phenotype, thus inhibited tumor metastasis." (PMID 40599798, 2025). "Given the aberrant expression of USP14 in CRC (MSI-H), we conducted a comprehensive study to examine its role in tumor progression and sensitivity to chemotherapy." (PMID 40316942, 2025). "For instance, USP14 is necessary to inhibit TRIM21-mediated K48 ubiquitination of IDO1, leading to increased IDO1 levels in colorectal cancer and promoting tumor cell immune evasion." (PMID 39990235, 2025). "We found that while LV significantly inhibited the tumor growth, tumor volume, and tumor weight of MDA-MB-231-derived xenograft tumors in vivo, the overexpression of USP14 significantly reversed these inhibitory effects of LV." (PMID 40497992, 2025).
tumor (continued). "To understand the relationship between intertumoral USP14 levels and RT effectiveness in HCC patients, we performed an IHC assay to assess the immunoreactive scores (IRS) of 77 pre-treatment tumor biopsies, clinically annotated from patients scheduled for RT." (PMID 40595451, 2025). "USP14 facilitates glycolytic activity in OSCC cells, thereby promoting tumor growth both in vivo and in vitro." (PMID 38388430, 2024). "In this work, we have also demonstrated for the first time that USP14 is a critical regulator of glycolysis in OSCC and verified a novel mechanism whereby it is involved in tumor metastasis and growth." (PMID 38388430, 2024). "To further examine the effects of USP14 on HCC progression in vivo, we constructed xenograft tumor models." (PMID 38993552, 2024). "Next, we observed the expression patterns of the USP14 protein in several OSCC cell lines and 70 tumor tissue specimens." (PMID 38388430, 2024). "Silencing USP14 increased the tumor antagonistic action of DDP in A549 cisplatin‐resistant (A549/DDP) cells, while USP14 overexpression decreased the antagonist effects." (PMID 37035133, 2023). "The results showed that USP14 expression was upregulated and positively correlated with JNK expression in various colorectal cell lines and patient tumor tissues." (PMID 36693850, 2023). "To probe into the functional roles of USP10, USP14, OTUB1, and STAMBP in HSC2 cells, we conducted assays to measure cell proliferation, in vitro invasion, and in vivo tumor growth." (PMID 37986681, 2023). "USP14, RPN11, and UCHL5 are three major regulatory DUBs of 26S proteasome, and their inhibitors also affect tumor development." (PMID 37190313, 2023). "The high abundance of USP14 and HSF1 in HNSCC indicated their key role as profound tumor-promoting factors, which is a previously unrecognized mechanism." (PMID 37686660, 2023). "Inhibiting USP14 lowers the IDO1 protein level, enhances the CD8 + T cells infiltration, reverses immune tolerance, as well as makes CRC tumor cells more sensitive to the anti-PD-1 therapy." (PMID 37658402, 2023). "B-AP15 (a USP14 and UCHL5 inhibitor) inhibits tumor growth in solid tumor models of squamous cell carcinoma, lung cancer, breast cancer, and colorectal cancer in vivo." (PMID 37190313, 2023). "WP1130 can partially selectively inhibit DUBs, which can directly inhibit deubiquitin activities of USP5, USP9X, USP14, UCH37, and UCH-L1, resist the proliferation and promote the apoptosis of various tumor cells." (PMID 37251574, 2023). "The expression of USP14 and HSF1 was significantly higher in HNSCC tumor tissues (T) than in the corresponding adjacent normal tissues (ANT)." (PMID 37686660, 2023). "The expression of USP14, USP21 and PSMD14 significantly increases within tumor tissue from liver cancer patients, which is negatively correlated with survival rate." (PMID 37251574, 2023). "The mechanistic experiments showed that the binding of MYH9 to NAP1L1, a potential promoter of tumor proliferation, inhibited the ubiquitination and degradation of NAP1L1 by recruiting USP14." (PMID 37770914, 2023). "Our study showed that USP10, USP14, USP18, USP32, USP33, and USP39 (termed as six-USPs) expressions were significantly elevated in tumor tissues." (PMID 36582601, 2022). "b‐AP15, an inhibitor of USP14 and UCHL5, exhibited potent tumour‐killing activity in BCR‐ABLWT and BCR‐ABLT315I CML cell lines, as well as in CML xenografts and primary CML cells." (PMID 36082692, 2022). "USP14 inhibition decreases IDO1 protein levels, reverses the immune tolerance of CRC tumors, and sensitizes CRC tumor cells to anti-PD-1 therapy." (PMID 36163134, 2022). "Our results demonstrated that the higher protein level of USP14 was not only positively correlated with that of the HIF1-α, but also closely related to the clinical stage, tumor differentiation, and patient prognosis of HCC." (PMID 34420039, 2021).
tumor (continued). "With the rapid growth of HCC, the tumor cells would respond to the adverse effects of hypoxia, HIF1-α protein level dramatically increases, at this time, highly expressed USP14 would be involved in the maintenance of HIF1-α protein stability." (PMID 34420039, 2021). "DUBs, ubiquitin carboxyl-terminal hydrolase L5 (UCHL5) and the ubiquitin-specific peptidase 14 (USP14), were detected in the cytoplasm of a high proportion of DLBCL tumor cells." (PMID 33923680, 2021). "PCAT6 promoted TNBC cell proliferation, migration, invasion, EMT, and angiogenesis, as well as tumor growth and metastasis via upregulation of VEGFR2 through sponging miR-4723-5p and recruiting USP14." (PMID 32908134, 2020). "Co-inhibition of USP14 and UCHL5 by novel DUB inhibitor VLX1570 revealed potent tumor-specific apoptotic activity in drug-resistant tumor cells of Waldenstrom macroglobulinemia (WM), an incurable non-Hodgkin lymphoma." (PMID 32354135, 2020). "b-AP15 mediated inhibition along with siRNA knockdown of USP14 and UCHL5 induces synergistic apoptotic activity in MM tumor cells and overcomes resistance to bortezomib." (PMID 32354135, 2020). "It has been reported that USP14 and UCHL5 are involved in the development of tumor and are potential new targets for proteasome inhibition in DLBCL." (PMID 31694672, 2019). "A recent study, for instance, showed that USP14 and UCHL5 were detected in tumor cell cytoplasm in 77 and 74% of the DLBCL cases, respectively." (PMID 31694672, 2019). "However, it remains unclear how USP14 contributes to tumor cell death and the autophagy pathway." (PMID 31653087, 2019). "b-AP15 inhibits USP14 and UCHL5 and was shown to inhibit tumor growth in multiple solid tumor mouse models and attenuated tumor invasion in acute myelogenous leukemia in in vivo models." (PMID 31396277, 2019). "Previous studies have shown that USP14 is highly expressed in patients with NSCLC, and it is related to tumor proliferation." (PMID 31653087, 2019). "In concert, these data provide further validation of USP14 and UCHL5 as bonafide targets in WM and the ability of VLX1570 to reduce WM cell growth in tumor bearing mice while extending their survival." (PMID 27813535, 2016). "We conducted extensive structure-activity relationship studies on WP1130, a Usp5/Usp9x/Usp14/UCH-L1/UCH-L5 inhibitor, to improve its safety, solubility and anti-tumor activity in mice." (PMID 24980819, 2014). "This suggests a potential role of USP14 and BAG4 in promoting tumor progression, while PRKN may act as a tumor suppressor in CRC (MSI-H)." (PMID 40316942, 2025). "Furthermore, b-AP15, a dual-targeting inhibitor of USP14 and UCHL5, promotes cell apoptosis and induces cell cycle arrest at the G2/M phase, as well as effectively suppresses tumor growth in nude mice." (PMID 40804247, 2025). "Furthermore, b-AP15, a dual-targeting inhibitor acting on USP14 and UCHL5, effectively suppressed tumor growth in nude mice." (PMID 40804247, 2025). "Further analysis across different tumor grades demonstrated a clear association between protein expression and disease severity: USP14 and BAG4 levels increased progressively with higher tumor grades, while PRKN expression decreased as the tumor grade advanced." (PMID 40316942, 2025). "The study highlights the USP14/BAG4/PRKN axis as a critical pathway in CRC (MSI-H), suggesting that targeting USP14 could inhibit tumor progression and improve chemotherapeutic outcomes." (PMID 40316942, 2025). "Therefore, We selected PKCα as the target protein for USP14 and UCHL5 due to its prominence in the PPI network and the lack of prior research connecting USP14 to the PKC family, offering new insights into tumor biology mechanisms." (PMID 40804247, 2025). "Furthermore, immunostaining of tumor samples, including MHCC97H xenografts and PDXs, showed a considerable decrease in GPX4 expression following IR treatment in cases where USP14 was deleted or inhibited in vivo." (PMID 40595451, 2025).